HIF1A (hypoxia inducible factor 1 subunit alpha)
Diseases named in the same sentence as HIF1A in open-access papers (continued):
Sharing a sentence is not in itself a finding about the gene and the disease.
cancer (continued). "PKM2 also promotes the Warburg effect by activation of the HIF-1α target genes SLC2A1, LDHA, and PDK1 that facilitate the shift from oxidative phosphorylation to glycolytic metabolism to meet the nutrient demands of cancer cell proliferation." (PMID 32408513, 2020). "Furthermore, HIF-1α and VEGF are novel biomarkers for cancer therapy and have led to a great shift in drug development." (PMID 32375802, 2020). "Ouabain suppressed the CoCl2-induced expression of HIF-1α in human skeletal muscle cells in a time- and concentration-dependent manner, consistent with suppressive effect of ouabain and other CTS on the HIF-1α abundance in cancer and smooth muscle cells." (PMID 33101052, 2020). "HIF-1α increases A2BR expression in HCC cells and cancer cell proliferation." (PMID 32351498, 2020). "In addition, the interactions among GRB2, EGFR, HIF1A, and SLC2A1 were also highly correlated with cancer in the KEGG “Pathways in cancer” (pathway #5200)." (PMID 32170141, 2020). "Furthermore, we confirmed that the Ras/MEK-RSK-ABCB1 and Ras/MEK-HIF-1α-FECH axes are involved in the regulation of PpIX accumulation in human cancers, as inhibition of RSK, HIF-1α, or ABCB1 increased PpIX accumulation in multiple human cancer cell lines." (PMID 33335181, 2020). "Hypoxia-inducible factor-1 alpha subunit (HIF-1α), a transcription factor usually induced in hypoxic conditions, has been demonstrated to contribute to angiogenesis and metastasis in several cancers including CRC." (PMID 33187272, 2020). "They inhibit the interaction of HIF-1α with VHL, increasing HIF-1α expression in cancer cells, but without enhancing transcription of HIF-1 target genes." (PMID 36046070, 2020). "After 1 d of treatment with CoCl2, the numbers of fluorescently labeled CT26 cells did not decrease, although HIF-1α upregulation was observed in CoCl2-treated CT26 cancer cells rather than in untreated cells." (PMID 32531897, 2020). "This is also supported by later studies showing the constitutive expression of HIF-1α in many cancer cell lines independent of hypoxic circumstances." (PMID 32631383, 2020). "HIF-1α could also be activated by the PI3K/AKT/mTOR signaling pathway, which is upregulated in numerous cancers including GRM1-expressing melanoma cells." (PMID 32937954, 2020). "Under hypoxia, HIF-1α can upregulate the expression of HEY1 and then recruit corepressors to inhibit the transcriptional activity of PINK1, reducing mitochondrial mass and promoting the growth of cancer cells." (PMID 32928258, 2020). "The expression of HIF1A was upregulated along with increasing TNM stage and in N1/2 cancers." (PMID 32630408, 2020). "Since PVT1/ miR-519d-3p and HIF-1A participate in regulating PDAC cancer progression and glycolysis, we researched whether PVT1/ miR-519d-3p functions through regulating HIF-1A." (PMID 32201527, 2020). "HIF-1α also controls lactate efflux via specialized monocarboxylate transporter – 4 (MCT4), as lactate production decreases cellular pH and is therefore toxic to cancer cells." (PMID 33028364, 2020). "Additionally, it is within possibility to imitate an intracellular hypoxic environment in vitro by utilizing the hypoxia-mimetic agent cobalt chloride (CoCl2), which promotes the induction of HIF-1α and EMT in several cultured carcinoma cell lines." (PMID 32599893, 2020). "Increased expression of HIF1α and HIF2α correlates with negative outcome of human tumors, and HIFs in cancer cells promote glucose metabolism and angiogenesis to help tumor proliferation and survival." (PMID 31717493, 2019).
cancer (continued). "1,25(OH)2D3 has been stated to upregulates HIF-1α via mTOR signaling in human monocytes and breast epithelial cells, while other studies uncovered that HIF-1α status is attenuated by 1,25(OH)2D3 treatment in human cancer cells." (PMID 30813930, 2019). "In cancer cells, nuclear p-STAT3-S705 can regulate the transcription of several autophagy-related genes such as BCL2 family members (e.g., BECN1, PIK3C3, CTSB, CTSL, PIK3R1, HIF1A, and BNIP3) and microRNAs with targets of autophagy modulators." (PMID 32565533, 2019). "Flow cytometry data showed that in these stable PC3 cell lines with high HIF-1α expression, ALM induced less apoptosis as compared with the empty vector (EV) control group, suggesting that HIF-1α is important for the suppressive effect of ALM in cancer cells." (PMID 31083403, 2019). "Matrine inhibits the mRNA and protein expression of HIF-1α, thereby suppressing the transcription of GLUT1, HK2, and LDHA, the downstream targets of HIF-1, which are the key enzymes involved in the glycolytic energy metabolism of cancer cells." (PMID 31849679, 2019). "To further confirm that HIF-1α is required for the recruitment of YAP, we assessed if HMGB1 promoted YAP binding to pluripotent genes promoter regions by CHIP in HIF-1α knockdown and control CD133− cancer cells." (PMID 31558702, 2019). "We found that protein instead mRNA level of HIF-1α rose in CD133− cancer cells following HMGB1 treatment in normoxia." (PMID 31558702, 2019). "Also, numerous studies in cancer cell lines (MCF-7, HepG2, H-1299, PC-3) showed that ROS acted through the PI3K/Akt signaling cascade, thereby enhancing HiF-1α expression and angiogenesis." (PMID 31766246, 2019). "HIF1α and ROS activation are responsible for regulating glucose transporter 1 (GLUT1), hexokinase II (HKII) and glutaminase expression and the reprogramming of cancer cell metabolism." (PMID 31514389, 2019). "As is confirmed that HIF1α commonly overexpresses in pejorative PCa, it’s reasonable for us to suspect that HIF1α might deteriorate PCa by accelerating autophagy and upregulating ATG5 to promote the cancer cell proliferation and migration in PCa." (PMID 31700698, 2019). "HIF-1α is a master transcriptional regulator that maintains HSC cell cycle regulation and activates the transcription of genes that are involved in critical aspects of cancer biology, including angiogenesis, cell survival, and invasion." (PMID 31640815, 2019). "In addition, MCU silencing in TNBC cells downregulates hypoxia-inducible factor 1-alpha (HIF1-α) expression, thus negatively affecting the expression of HIF1-α target genes involved in cancer progression." (PMID 31178978, 2019). "HIF-1α and GLUT-1 are important markers of hypoxia in the cancer microenvironment." (PMID 31105886, 2019). "Moreover, Scarpa and colleagues explored the influence of AVAs on the modulation of two pro-survival genes in cancer cells: the vascular-endothelial growth factor (VEGF) and the hypoxia-inducible factor 1-alpha (HIF1A)." (PMID 31540249, 2019). "Relevant in cancer progression is the functional interaction between LSD1 and HIF-1α." (PMID 30866496, 2019). "In cancer, stabilized HIF-1α activates transcriptional programs that have been recognized to induce the epithelial to mesenchymal transition (EMT) and support metastasis in various cancer types." (PMID 31536495, 2019). "Given the multiple mechanisms that regulate HIF1α, it is likely that alternate mechanisms will be identified across different cancer types, and hence further studies are needed to explore approaches for targeting HIF1 in specific cancer settings." (PMID 30754624, 2019).
cancer (continued). "Reactive oxygen species produced by catabolic cancer cells and the downregulation of the Krebs cycle enzyme isocitrate dehydrogenase 3α (IDH-3α) upregulates HIF-1α and NADH dehydrogenase (ubiquinone) 1 alpha subcomplex, 4-like 2 (NDUFA4L2), which in turn inhibits OXPHOS and promotes CAF glycolysis." (PMID 31683709, 2019). "HIF1A and VEGFA (vascular endothelial growth factor A) are the two genes shared by the four diseases in both the HIF-1 signaling pathway and the pathways in cancer." (PMID 30700303, 2019). "Furthermore, YAP knockdown significantly decreased HIF-1α expression and inhibited HMGB1/TLR2 induced CD133− cancer cell dedifferentiation." (PMID 31558702, 2019). "The contribution of areca nut extract to autophagy may be explained by ROS generation or hypoxic condition in cancer cells, following the stimulation by various signaling pathways of PI3/AKT, MEK/ERK, AMPK/mTOR, or HIF-1α 63, 65-66." (PMID 31417650, 2019). "HIF1α immunofluorescence analysis confirmed its expression in cancer but not in normal control organoids." (PMID 30814510, 2019). "A deep understanding and the control of HIF-1α and VEGF interaction could be beneficial to develop novel strategies for cancer therapy." (PMID 30871059, 2019). "In addition, cancer stem cell (CSC) markers, OCT4 and Notch, are induced by HIF1α and promote stem cell renewal." (PMID 31514389, 2019). "In addition, HSP90 activates HIF-1α and NF-kB, which together enhance the oncogenic events such as cancer cell EMT, invasion, and motility that together confer metastasis of cancer." (PMID 31878360, 2019). "In combination with FEC/TE, I2 treatment exhibited a synergic effect on cancer cell apoptosis and impaired expression of chemoresistance markers (BIRC5 and HIF1A) as well as changes in the expression of specific EMT markers (increased E-cad expression and decreased Vimentin expression)." (PMID 31319484, 2019). "In several cancers, including HNSCC, the expression of glucose transporter 1 (GLUT1) is often elevated, and in conjunction with enhanced mTOR signalling (mTORC1 and C2), the pair activates key oncogenic drivers, including c-MYC and HIF-1α." (PMID 30970654, 2019). "HIF1α is a major cellular regulator which plays a critical role in KSHV-mediated oncogenesis and is known to interact at the transcriptional and post-transcriptional levels with KSHV factors to promote the cancer phenotype." (PMID 31479497, 2019). "Since N-cadherin and Vimentin have been proved usually positive in various cancer metastases, we speculated the downregulation of ATG5 might impact the HIF1α-induced metastasis ability of PC-3 cells." (PMID 31700698, 2019). "YAP and HIF-1α were primarily detected in the cytoplasm of cancer cells without HMGB1 treatment, while displayed distinct nuclear localization following rhHMGB1 treatment." (PMID 31558702, 2019). "Consequently, YAP and HIF-1α form complex in the nucleus and further induce CD133− cancer cells dedifferentiation." (PMID 31558702, 2019). "Whereas the control tumors expressed HIF-1α in their cancer cell nuclei, 143B−/− masses were characterized by a complete absence of HIF-1α staining, in line with MIF downregulation." (PMID 31835761, 2019). "However, whereas it was clearly demonstrated that HIF-1α and HIF-2α are key regulators of the hypoxia response and of tumorigenesis, the roles played by HIF3α, either in hypoxia or in cancer promotion are far less clear." (PMID 31151160, 2019). "HIF1α and AMPK also exert antagonistic effects in inflammatory microenvironments, e.g. in cancer." (PMID 31440740, 2019). "Moreover, HRE luciferase activity, indicated HIF-1α DNA binding ability, was enhanced in HMGB1 treated CD133− cancer cells and suppressed in the presence of EP under hypoxia." (PMID 31558702, 2019). "Interestingly, different studies have shown that intratumoral hypoxia and the resulting upregulation of HIF1A and HIF2A signaling correlate with increased cancer patient mortality." (PMID 31159361, 2019).
cancer (continued). "Consistent with this pattern, an increase in the level of extracellular SOD may also suppress the hypoxic accumulation of HIF-1α and its downstream target gene VEGF in several different types of cancer cells." (PMID 31583051, 2019). "HIF-1α, a chief target for cancer treatment, interacts with VEGF and stimulates the development of new blood vessels, which in turn provide a sufficient supply of oxygen to cancer cells for their progression." (PMID 30871059, 2019). "Cancer studies indicate that YAP and HIF-1α may interact to promote glycolysis as YAP may localize to the nucleus and prevent HIF-1α degradation." (PMID 31380363, 2019). "In epithelial carcinomas, ST6GAL1 expression confers increased resistance to chemotherapy, hypoxia, and nutrient deprivation by promoting a stem-like phenotype, bolstering signaling through pro-survival and pro-proliferative EGFR, HIF-1α, and NF-κB pathways." (PMID 31408003, 2019). "In addition, ISLA reduced the levels of pro-angiogenic factors such as MMP-9, PlGF, and VEGF in HT1080 CM via suppression of the HIF-1α/Akt/mTOR pathway, supporting the anti-angiogenic activity of ISLA in cancer cells." (PMID 30618749, 2018). "However, targeting the neddylation pathway with an MLN4924 treatment stabilized the hypoxia-inducible factor 1A (HIF1A), which is one of the main transcriptional enhancers of the immune checkpoint molecule PDL1 (programmid death ligand-1) in cancer cells." (PMID 30393513, 2018). "Furthermore, we demonstrated that a functional cooperation between HIF-1α and GPER contributes to VEGF regulation in cancer cells exposed to copper." (PMID 29996493, 2018). "Under these conditions the growth advantage of cancer cells over nonmalignant cells depends on cancer cell adaptation to glycolysis and is driven by the transcription factor hypoxia-inducible factor 1α (HIF1α) which is stabilized by hypoxia." (PMID 30123774, 2018). "Nonetheless, molecule inhibitory drugs reducing HIF-1α levels, or targeting HIF1 stability/activity may provide interesting benefits in anti-cancer therapy." (PMID 30301213, 2018). "Besides these transcription factors which are well studied for PPIi, many others are already, or envisaged to be, targeted by peptidomimetics or synthetic inhibitors for cancer treatment (androgen receptor/TIF2, HIF1α/p300-CBP, HOX/PBX, YAP/TEAD)." (PMID 29921764, 2018). "HIF-1α induces the over-expression of several glycolytic proteins including glucose transporters (i.e., GLUT1 and GLUT3), and enzymes such as hexokinase-1 (HK1), HK2 and LDHA in cancer cells." (PMID 30619850, 2018). "Moreover, LW6, an HIF1α inhibitor, reduced EMT, cancer invasion, and the levels of Twist in sh-PIMT A549 cells." (PMID 29568357, 2018). "Although the role of HIF-1α/VEGF in villous angiogenesis is unknown, given the similarities between trophoblasts and cancer cells, we predict that its role in the placenta may be similar to its role in cancer, where it promotes angiogenesis." (PMID 29951709, 2018). "Since no CUL2 mutation was found to play a critical role in HIF-1α activation in several cancers, it is likely that HIF-1α loss of homeostasis in cancer is mediated primarily by deregulation of cullin expression rather than cullin point mutations." (PMID 29594129, 2018). "In agreement, our data from functional assays demonstrated that both OSA monocytes and monocytes from IH in vitro models exhibited high expression of HIF1α and VEGF, together inducing a cancer cell-promoting phenotype, whereas interfering assays reverted this phenotype." (PMID 29997451, 2018).
cancer (continued). "In ccRCC tissues, FSTL1 was negative or detected in the cytoplasm of cancer cells; HIF-1α and HIF-2α were positive in 52.9% (45/85) and 66.7% (52/78) of ccRCC cases, respectively." (PMID 29357946, 2018). "HIF-1α protein levels are tightly regulated through ubiquitin-mediated proteosomal degradation; however, high levels of HIF-1α is a common feature in many solid tumors and is thought to enhance cancer cell proliferation, migration, and survival." (PMID 29628507, 2018). "Both HIF-1α and HIF-2α have been found overexpressing in various cancers, including BC." (PMID 30135144, 2018). "In addition, our group had shown that increasing GO with DCA was sufficient to decrease HIF1α activity, providing a strong positive feedback loop that would potentiate the increase in the GO/GLY ratio, in cancer." (PMID 29951485, 2018). "Once HIF-1α becomes stabilized and activated under hypoxic conditions, it, in combination with HIF-1β, induces the expression of hundreds of genes responsible for malignant cancer progression." (PMID 29535824, 2018). "Overexpression of miR-210 in cancer cells may contribute to a persistent function of HIF-1α by regulating HIF-3α and other targets, leading to the progression of the cancer by attenuating cell proliferation and increasing drug resistance." (PMID 29953500, 2018). "However, it has only been reported that LOX expression is regulated by HIF-1α under hypoxia and is induced by TGF-β in cancer cells." (PMID 29472856, 2018). "Moreover, the HIF1α inhibitor reduced EMT, cancer invasion, and the protein levels of Twist in sh-PIMT A549 cells." (PMID 29568357, 2018). "In addition, HIF-1a and nuclear factor kappa B (NFkB) are involved in EMT by elevating snail expression in cancer cells." (PMID 29661250, 2018). "Thus, in hypoxic tumors, HIF-1α regulates many genes involved in cancer development and SPHK-1 regulates and stabilizes HIF-1α through the AKT/GSK-3β pathway." (PMID 28165392, 2017). "Numerous compounds are reported to inhibit HIF-1α expression, but no HIF-1α inhibitors are clinically available as anti-cancer drugs." (PMID 29152137, 2017). "Similarly, STAT3 has been shown to work with HIF1α in order to activate downstream targets in various cancers, and we have previously shown that APE1 interacts with both STAT3 and HIF1α under hypoxia." (PMID 28922540, 2017). "Recent studies indicated that both HIF-1α and VEGFA could be regulated by miRNAs in many kinds of cancers." (PMID 28399173, 2017). "Stabilization of HIF-1α in the absence of oxygen stimulates the expression of numerous hypoxia-response genes that promote the survival of cancer cells in an unfavorable environment." (PMID 28045438, 2017). "HIF-1α and HIF-2α are commonly upregulated during cancer progression." (PMID 28423608, 2017). "Under hypoxic conditions, HIF-1α is no longer degraded and translocated to the nucleus regulating hundreds of genes, and many of them play important roles in cancer cell metabolism." (PMID 29026004, 2017). "In addition to CAIX, tumors expressing HIF-1α frequently express high levels of other pH-regulating enzymes, the lactate/H+ transporters MCT1 and MCT4 albeit co-expression in the same cancer cells only partially overlaps." (PMID 28099149, 2017). "Recent studies reported that miR-150 could regulate HIF-1α and VEGFA by targeting in many kinds of cancers." (PMID 28399173, 2017). "There appears no clear connection in the effect of Ca2+ and HIF-1α on NDRG1 induction in cancer cells." (PMID 28045438, 2017). "It has been reported that hypoxia mediates the uptake of NIRF dye by different cancer cells via the activation of HIF1α/OATP signalling, which, considering the common molecular aspects shared by different types of cancers, may apply to HCC as well." (PMID 28915639, 2017).